NUP210L (nucleoporin 210 like)
Synonyms: SPGF97
Tractability: Antibody: UniProt predicts a signal peptide or a membrane-spanning region. PROTAC: ubiquitination databases record sites on it.
Gene: Protein-coding gene on chromosome 1 (153,992,690 to 154,155,116, reverse strand). Ensembl gene ENSG00000143552.
Subcellular location: Nucleus membrane
Subcellular location (Human Protein Atlas): Nuclear bodies; Cytosol
Gene Ontology:
Cellular component: nuclear membrane; nuclear pore
Genetic constraint (gnomAD): Loss-of-function variants: 49 observed, 147.65 expected, observed/expected ratio (o/e) 0.33, 90% interval 0.26 to 0.42. The upper end of that interval is the gene's LOEUF score, 0.42, which puts it in group 1 of 6, group 1 being the genes least tolerant of losing a copy. Missense variants: 1,364 observed, 1,825.7 expected, observed/expected ratio (o/e) 0.75, 90% interval 0.71 to 0.78. Synonymous variants: 595 observed, 668.75 expected, observed/expected ratio (o/e) 0.89, 90% interval 0.83 to 0.95.
Homologues: Orthologues: chimpanzee NUP210L (99% identical), rabbit NUP210L (89% identical), dog NUP210L (88% identical), mouse Nup210l (83% identical), rat Nup210l (82% identical), pig NUP210L (81% identical), macaque NUP210L (34% identical), Caenorhabditis elegans npp-12 (23% identical), Drosophila melanogaster Gp210 (22% identical). Paralogues in human: NUP210 (45% identical).
Diseases named in the same sentence as NUP210L in open-access papers:
NUP210L is named in the same sentence as 6 diseases in open-access papers, as found by Europe PMC text mining. Sharing a sentence is not in itself a finding about the gene and the disease. The quoted sentences say what the papers report.
Alzheimer disease (1 paper, 2026). A progressive, neurodegenerative disease characterized by loss of function and death of nerve cells in several areas of the brain leading to loss of cognitive function such as memory and language. "In replication analyses, 21 genes showed nominal support in UK Biobank and Alzheimer's Disease Genetics Consortium (ADGC) cohorts, with eight genes (TREM2, ACADS, MFSD12, NUP210L, PIEZO2, PSEN1, SMURF2, AKAP13) supported under identical masks." (PMID 41960309, 2026).
breast carcinoma (1 paper, 2024). "We identified four new genes (CTD-3080P12.3, EN1, LINC01956, and NUP210L) showing a significant association with breast cancer risk at the Bonferroni-corrected significance level." (PMID 38697998, 2024). "We also found that two exon junctions in genes BRD9 and NUP210L showed an association with overall breast cancer risk at the Bonferroni-corrected significance of P < 4.3 × 10−6 (0.05/11, 426)." (PMID 38697998, 2024). "NUP210L was found to be associated with overall breast cancer risk." (PMID 38697998, 2024). "NUP210L was not located at any known breast cancer risk locus and has not been reported by any previous breast cancer TWAS." (PMID 38697998, 2024). "At Bonferroni-corrected P < 0.05, we identified six genes associated with breast cancer risk, including four genes not previously reported (CTD-3080P12.3, EN1, LINC01956 and NUP210L)." (PMID 38697998, 2024).
cancer (1 paper, 2025). A tumor composed of atypical neoplastic, often pleomorphic cells that invade other tissues. "Upregulation of RGPD6, RGPD5, RGPD8, RGPD2, NUP210L, and PLCL1 has been observed in invasive tumors, implicating this functional network in the remodeling of ECM stiffness and integrin signaling, both of which enhance cancer cell migration." (PMID 40370715, 2025).
tumor (1 paper, 2024). "Six rare fusion partners were also identified: GOPC, MPRIP, NUP210L, ZCCHC8, CCDC6, and CFAP53, each present in one tumor." (PMID 38835380, 2024).
NUP210L also shares sentences with these, for which no sentence is quoted: asthma (1 paper); lung carcinoma (1).